BMP1 (bone morphogenetic protein 1)
Diseases named in the same sentence as BMP1 in open-access papers (continued):
Sharing a sentence is not in itself a finding about the gene and the disease.
craniosynostosis (1 paper, 2024). Craniosynostosis is defined as the premature fusion of one or more cranial sutures leading to secondary distortion of skull shape resulting in skull deformities with a variable presentation. "In short words, this study revealed Periostin/BMP1 axis’s role in coronary craniosynostosis in TWIST1+/− mice by deeply exploring SMSC proliferation and osteogenic differentiation." (PMID 38369459, 2024). "This insight not only unveiled a novel regulatory axis within the cellular milieu of craniosynostosis but also accentuated the intricate molecular dialogue between Periostin and BMP1." (PMID 38369459, 2024). "Collectively, these findings not only highlighted the efficacy of Periostin overexpression in mitigating craniosynostosis in TWIST1+/− mice but also underscored the critical involvement of the Periostin/BMP1 axis in craniosynostosis." (PMID 38369459, 2024). "This study aims to further explore the functions and regulatory mechanisms of Periostin and BMP1 in craniosynostosis, analyze the Periostin/BMP1 axis in the proliferation and osteogenic differentiation of SMSCs, and explore its interaction with mutations in the TWIST1 gene." (PMID 38369459, 2024). "In addition, understanding the specific signal transduction pathways and downstream targets in which Periostin/BMP1 regulates coronary craniosynostosis is a potential direction for further research." (PMID 38369459, 2024). "Conducting broader population studies, including analyzing samples from patients with craniosynostosis, could better validate the Periostin/BMP1 axis." (PMID 38369459, 2024). "This study explored the Periostin/BMP1 axis in regulating SMSC proliferation and osteogenic differentiation and revealed its effect on craniosynostosis in TWIST1+/− mice." (PMID 38369459, 2024). "Although our findings showed a regulatory role of the Periostin/BMP1 axis in both mouse models and SMSC models for craniosynostosis, we need to further correlate these findings with clinical data related to human diseases." (PMID 38369459, 2024).
endometriosis (1 paper, 2022). The growth of functional endometrial tissue in anatomic sites outside the uterine body. "In a recent study, the researchers found that treatment with anti-bone morphogenetic protein 1 (anti-BMP1) antibodies dose-dependently increased lesion volume in mice with endometriosis, reduced IL-17 and IL-1β levels." (PMID 35582411, 2022).
exfoliation syndrome (1 paper, 2025). An autosomal dominant disorder caused by mutations in the LOXL1 gene, encoding lysyl oxidase homolog 1. "Interestingly, the predicted BMP-1 cleavage site at position 134 is located near the exfoliation syndrome (XFS)-associated coding variants at positions 141 (R141L) and 153 (G153D), suggesting that changes in LOXL1 processing may play a role in the pathogenesis of XFS (Aung, Chan & Khor, 2018)." (PMID 40786111, 2025).
glioblastoma (1 paper, 2015). The most malignant astrocytic tumor (WHO grade IV). "The expression levels of LOX, BMP1 and HIF1A were correlated and analyzed according to IDH1 mutation status and to the clinical end-point of overall survival of glioblastoma patients." (PMID 25790191, 2015).
gout (1 paper, 2024). A condition characterized by painful swelling of the joints, which is caused by deposition of urate crystals. "ADH1B (OR = 0.15, 95% CI = 0.07–0.35), BMP1 (OR = 7.04, 95% CI = 3.35–14.78), and HIST1H3A (OR = 205.85,95%CI = 78.35–540.8) were found to be significantly associated with gout at the Bonferroni-corrected threshold (P 1.719 10 − 6)." (PMID 38831441, 2024). "Through a Mendelian randomization (MR) analysis, we identified three proteins causally associated with gout: ADH1B, BMP1, and HIST1H3A." (PMID 38831441, 2024). "This study determined three proteins causally associated with gout by Mendelian randomization (MR) analysis: ADH1B, BMP1 and HIST1H3A." (PMID 38831441, 2024). "The BMP-1 protein, through its regulatory effects on uric acid metabolism and immune cell function, offers new opportunities for intervention in the treatment of gout." (PMID 38831441, 2024).
Hernia (1 paper, 2023). "Direct involvement of BMP1 both in male sexual development and hernia genesis makes it a strong candidate for linking the two pathologies, PSW and multiple hernias, observed in the present case." (PMID 38021525, 2023).
hypercholesterolaemia (1 paper, 2023).
leukemia (1 paper, 2017). A malignant (clonal) hematologic disorder, involving hematopoietic stem cells and characterized by the presence of primitive or atypical myeloid or lymphoid cells in the bone marrow and the blood.
liver cirrhosis (1 paper, 2020). "In our study, BMP1 showed a lower peak intensity in HCC patients with normal AFP levels than liver cirrhosis patients." (PMID 31979338, 2020). "In addition to BMP1 (0.8, cancer/liver cirrhosis, p = 0.013), Trim22 was less abundant in HCC patients with normal AFP than liver cirrhosis patients, and this difference was statistically significant (0.6, cancer/liver cirrhosis, p < 0.001)." (PMID 31979338, 2020).
lung adenocarcinoma (1 paper, 2013). A carcinoma that arises from the lung and is characterized by the presence of malignant glandular epithelial cells. "CDK13, BMP1, RNF13, MAT2A, CHRNA4 are also among the genes in Merged-module whose over-expression has been reported in different cancers, however, their over-expression has been demonstrated in lung adenocarcinoma in this study." (PMID 23874428, 2013).
malnutrition (1 paper, 2025). Inadequate nutrition resulting from poor diet, malabsorption, or abnormal nutrient distribution. "Given the importance of tracking growth velocity in child development – it allows for early detection of growth abnormalities and potential health issues, such as malnutrition, delayed puberty, or precocious puberty – our findings highlight the potential value of serum BMP1 as a biomarker." (PMID 41247840, 2025).
Marfan syndrome (1 paper, 2015). A disorder of the connective tissue. "Our study suggests that DPY-31 in C. elegans and BMP-1 in humans may be involved in TGFβ dysregulation, a process that has been implicated in Marfan syndrome disease progression." (PMID 25917920, 2015).
metabolic syndrome (1 paper, 2019). A cluster of metabolic risk factors for CARDIOVASCULAR DISEASES and TYPE 2 DIABETES MELLITUS. "In a murine model of diet-induced metabolic syndrome (high-fat high-simple carbohydrate, HFHSC) no changes were observed in the cardiac expression of Lox and Loxl3; however, metabolic syndrome significantly upregulated Bmp1, which increased LOX processing and activity and CCL." (PMID 31766500, 2019).
metastatic tumors (1 paper, 2025). "We looked at the TGFβ-1, CXCR4, BMP1, VCAN, and WNT2 expression profiles in a few BC datasets related to primary and metastatic tumors." (PMID 41348904, 2025). "TGFβ-1, CXCR4, BMP1, VCAN, and WNT2 are more expressed in original tumors compared to metastatic tumors, according to the data." (PMID 41348904, 2025).
muscular dystrophy (1 paper, 2020). Muscular dystrophy (MD) refers to a group of more than 30 genetic diseases characterized by progressive weakness and degeneration of the skeletal muscles that control movement. "A LASSO regression analysis identified three hub genes: Recombinant Bone Morphogenetic Protein 1 gene (BMP1), Duchenne muscular dystrophy gene (DMD) and mitogens induced GTP-binding protein gene (GEM)." (PMID 32953253, 2020).
Myocardial fibrosis (1 paper, 2020). "In addition, other research also demonstrated that sFRP2 can play a role in reducing myocardial fibrosis via regulating the BMP1 pathway." (PMID 32071544, 2020).
osteoarthritis (1 paper, 2022). A noninflammatory degenerative joint disease occurring chiefly in older persons, characterized by degeneration of the articular cartilage, hypertrophy of bone at the margins and changes in the synovial membrane. "CALC2 level was measured after in vitro cleavage of recombinant type II collagen with bone morphogenetic protein-1 (BMP-1) and treatment of ex vivo human osteoarthritis (OA) cartilage explant model (HEX) with insulin-like growth factor-1 (IGF-1)." (PMID 36613894, 2022).
ovarian carcinoma (1 paper, 2025). A malignant neoplasm originating from the surface ovarian epithelium. "Several of the analyzed genes (TGFβ-1, IL19, CXCR4, BMP1, VCAN, and WNT2) showed elevated expression across multiple cancer types in pan-cancer datasets, including lung, colon, and ovarian cancers." (PMID 41348904, 2025).
pancreatitis (1 paper, 2021). Inflammation of the pancreas. "We performed peptide level analysis to survey BMP1’s other targets and found that HSPG2 LG3 domain is partially but significantly retained in diseased tissues (PanIN, pancreatitis, and PDAC) as compared to normal pancreas." (PMID 33879793, 2021).
preeclampsia (1 paper, 2024). Preeclampsia is a hypertensive disorder of pregnancy that is characterized by new-onset hypertension with proteinuria presenting after 20 weeks of gestation, and depending on mild or severe forms may initially present with severe headache, visual disturbances, and hyperreflexia. "In multivariate analysis, signal peptide complement C1r/C1s, Uegf, and Bmp1, and epidermal growth factor-containing protein 1 was determined as an independent predictor for preeclampsia (OR: 1.678, 95%CI 1.424-1.979, p<0.001)." (PMID 38451587, 2024). "Blood samples were taken from all patients with preeclampsia to measure signal peptide complement C1r/C1s, Uegf, and Bmp1, and epidermal growth factor-containing protein 1 levels at the time of hospitalization." (PMID 38451587, 2024).
prostate (1 paper, 2023). "Inferred CNV from our high resolution single nucleus analysis identifies Chr8p loss (containing NKX3–1, BMP1, FGFR1 genes and multiple microRNAs) as one of the earliest genetic events in prostate tumorigenesis, shared by >43% of cancer cells in GS6 tumors." (PMID 37327786, 2023).
pulmonary embolism (1 paper, 2023). The obstruction of the pulmonary artery or one of its branches by an embolus, sometimes associated with infarction of the lung. "This study aimed to investigate the potential application of plasma signal peptide‐complement C1r/C1s, Uegf and Bmp1‐epidermal growth factor domain‐containing protein 1 (SCUBE‐1) as a biomarker in the diagnosis of pulmonary embolism (PE)." (PMID 36748401, 2023).
renal carcinoma (1 paper, 2020). A carcinoma arising from the epithelium of the renal parenchyma or the renal pelvis. "High BMP1 expression is significantly positively correlated with disease progression, which identifies BMP1 as an independent predictor of prognosis in ccRCC patients and is involved in the development of renal cancer." (PMID 31155610, 2020). "Taken together, these results demonstrated that BMP1 reducing could inhibit renal cancer growth." (PMID 31155610, 2020).
renal cell carcinoma (1 paper, 2025). "In accordance, high expression of BMP-1 was associated with EMT, angiogenesis, hypoxia pathway, KRAS signaling and shorter overall survival in renal cell carcinoma." (PMID 39792296, 2025). "For example, knockdown of BMP-1 suppresses malignancy in renal cell carcinoma." (PMID 39792296, 2025).
rhabdoid tumor (1 paper, 2021). An aggressive malignant embryonal neoplasm usually occurring during childhood. "It is notable, the peaks in BMP1 as well as multiple other genes overlapped with published ATAC‐seq peaks that were gained following SMARCB1 complementation in rhabdoid tumor cells (Fig EV4)." (PMID 33332735, 2021).
tumor (39 papers, 2010 to 2025). "Overall, our results reveal that high expression of BMP1 in ccRCC is associated with poor prognosis and tumor immune infiltration through ncRNAs." (PMID 37848987, 2023). "Our results demonstrate that ncRNA-mediated high expression of BMP1 is associated with poor prognosis and tumor immune infiltration in ccRCC." (PMID 37848987, 2023). "Previous research methods explored the underlying value of BMP1 in tumor immunotherapy and the connection of BMP expression with m6A modification and immune invasion." (PMID 36267461, 2022). "Previous high-throughput screening has identified BMP1 RNA sequences as the most upregulated transcripts in human tumor endothelium associated with angiogenesis." (PMID 31155610, 2020). "Moreover, BMP1 has been implicated in tumor progression by inducing the initial cleavage and release of complexes." (PMID 36267461, 2022). "In addition, current understanding regarding the association between BMP1 and tumor immune infiltration in ccRCC remains unclear." (PMID 37848987, 2023). "Our results further support these finding and demonstrate tumor-promoting role of BMP-1 in highly aggressive metastatic mammary carcinoma." (PMID 39792296, 2025). "In vivo, lenti-BMP1 primary tumours were smaller than those of the controls (~100 mg vs. ~210 mg (p < 0.01)) and shCOL1A1 (~500 mg) or lenti-BMP1 + shCOL1A1 (600 mg) tumours." (PMID 37627163, 2023). "Metastasis was also significantly reduced in lenti-BMP1 tumours compared to the controls (~0.02 vs. ~0.3 lung met load/g tumour (p < 0.01))." (PMID 37627163, 2023). "To further study the role of BMP1 in tumor immunity, we investigated relationships between expression of BMP1 and biomarkers of immune cells in ccRCC." (PMID 37848987, 2023). "Whereafter, the latent influences of BMP1 were analyzed, respectively, acting on tumor microenvironment, TMB, and MSI." (PMID 36267461, 2022). "Comparing the tumor groups with normal groups, the expression of BMP1 was significantly related in 14 cancer types based on TCGA data." (PMID 36267461, 2022). "BMP1 is considered to be a key factor in promoting tumor growth and metastasis of LC, and BMP1 facilitates NSCLC metastasis by inhibiting TGF-β activity in NSCLC." (PMID 36245844, 2022). "More interestingly, the expression of BMP1 was prominently related to tumor immune checkpoint blockade treatment." (PMID 36267461, 2022). "Meanwhile, orthotopic injection of BxPC3 cells knocked down for BMP1 expression by shBMP1 resulted in slightly increased tumor weight, and lung and liver metastasis loads." (PMID 33879793, 2021). "Orthotopic injections of lenti-BMP1 PANC1 cells exhibited major reductions in both primary tumor weight and liver metastasis load." (PMID 33879793, 2021). "Here, we showed that BMP1 can suppress tumor growth and metastasis in PDAC models by promoting fibrillar collagen deposition, but only in cancer cells expressing substantial amounts of collagen." (PMID 33879793, 2021). "Orthotopic injection of oe-BMP1 BxPC3 cells led to a decrease in primary tumor weight and a marked reduction in normalized lung and liver metastasis load." (PMID 33879793, 2021). "In fact, we found that the extent of tumor growth suppression by BMP1 correlated linearly with the endogenous COL1A1 expression levels." (PMID 33879793, 2021). "Combining the results from both overexpression and knockdown/inhibition experiments, we conclude that BMP1 suppresses tumor growth and metastasis in the BxPC3 cells." (PMID 33879793, 2021). "In HCC, this lncRNA controls the miR-29c/BMP1 axis and thereby promotes tumor cell proliferation, EMT, and metastasis via activating MEK/ERK signaling." (PMID 33602223, 2021). "Altogether, we showed that BMP1 depends on cancer-cell-derived COL1A1 for its function to suppress PDAC tumor growth and metastasis." (PMID 33879793, 2021).
tumor (continued). "We found that the primary tumor growth and lung and liver metastasis load resembled the in vitro growth results, in which lenti-BMP1 reduced and shCOL1A1 promoted tumor growth and metastasis, and shCOL1A1 completely rescued the suppression by lenti-BMP1." (PMID 33879793, 2021). "This study is the first study to demonstrate the functional role of BMP1 in ccRCC tumor progression." (PMID 31155610, 2020). "Matrix metalloproteinases (MMPs), cathepsins, and bone-morphogenetic protein-1 release fragments, which regulate physiopathological processes including tumor growth, metastasis, and angiogenesis, a pre-requisite for tumor growth." (PMID 26869928, 2016). "In contrast to active LOX, the LOX propeptide (LOX-PP) generated during the course of BMP-1-mediated LOX activation in the ECM acts as a tumor suppressor through multiple signaling pathways." (PMID 24265769, 2013). "Few studies documented direct tumor-promoting features of BMP-1." (PMID 39792296, 2025). "Moreover, our findings revealed a significant positive correlation between BMP1 levels and tumor immune cell infiltration, biomarkers of immune cells, and immune checkpoint expression." (PMID 37848987, 2023). "Furthermore, we found that BMP1 levels correlated significantly positively with tumor immune cell infiltration, biomarkers of immune cells, and immune checkpoint expression." (PMID 37848987, 2023). "The tumor microenvironment (TME) landscapes we constructed implied that BMP1 may have a crucial effect on macrophage polarization." (PMID 36267461, 2022). "Moreover, the correlation between BMP1 and tumor microenvironment was analyzed using ESTIMATE and CIBERSORT algorithms." (PMID 36267461, 2022). "In summary, BMP1 in cancer cells drives ColI deposition, more so from cancer cells than from stromal cells, possibly because BMP1, although a secreted proteinase, can also function intracellularly and thereby affects most strongly the collagen produced by the tumor cells overexpressing it." (PMID 33879793, 2021). "Furthermore, the effect of BMP1 on tumor progression and metastasis depends upon the level of cancer-cell-derived collagens." (PMID 33879793, 2021). "Thus cancer-cell-derived ColI is critical for BMP1’s effects on tumor progression, whereas stromal-cell-derived ColI is either less, or not, important in this particular role, despite its prevalence." (PMID 33879793, 2021). "Although BMP1, as a secreted proteinase, promotes fibrillar collagen deposition from both cancer cells and stromal cells, only cancer-cell-derived procollagen cleavage and deposition suppresses tumor malignancy." (PMID 33879793, 2021). "We therefore investigated whether PCOLCE could enhance the anti-tumorigenic role of BMP1, which, if so, could suggest that BMP1 suppresses tumor growth and metastasis through cleavage of fibrillar collagens." (PMID 33879793, 2021). "In summary, PCOLCE enhanced BMP1 suppression of metastasis and perhaps primary tumor growth, which supports the hypothesis that BMP1 acts via cleavage of procollagens to suppress tumor growth and metastasis." (PMID 33879793, 2021). "This study suggests that tumor epithelial BMP1/COL1A1 expression may be a positive prognostic factor, although bulk fibrillar collagen level was shown to correlate negatively with patient survival." (PMID 33879793, 2021). "The tumor growth suppression role of BMP1 and cancer-cell-derived ColI may be due to the ratio imbalance of the ColI homotrimer and heterotrimer, which may have differential impacts on cancer cells, induced by BMP1 manipulation." (PMID 33879793, 2021). "The roles of BMP1 and cancer-cell-derived fibrillar collagens in suppressing tumor growth and metastasis reported here and the well accepted pro-tumorigenic roles of stromal-cell-derived fibrillar collagen clearly illustrate the functional complexity of fibrillar collagens in PDAC." (PMID 33879793, 2021).